WEE1 (WEE1 G2 checkpoint kinase)
Description:
Acts as a negative regulator of entry into mitosis (G2 to M transition) by protecting the nucleus from cytoplasmically activated cyclin B1-complexed CDK1 before the onset of mitosis by mediating phosphorylation of CDK1 on 'Tyr-15'. Specifically phosphorylates and inactivates cyclin B1-complexed CDK1 reaching a maximum during G2 phase and a minimum as cells enter M phase. Phosphorylation of cyclin B1-CDK1 occurs exclusively on 'Tyr-15' and phosphorylation of monomeric CDK1 does not occur. Its activity increases during S and G2 phases and decreases at M phase when it is hyperphosphorylated. A correlated decrease in protein level occurs at M/G1 phase, probably due to its degradation.
Synonyms: WEE1hu; WEE1A
Tractability: Small molecule: a drug acting on it is in phase 2 or 3 trials; a structure with a bound ligand is known; a high-quality ligand is known; it has a high-quality binding pocket; it belongs to a druggable protein family. PROTAC: it is named in the literature on targeted protein degradation; UniProt records ubiquitination sites on it; ubiquitination databases record sites on it; a small molecule that binds it is known.
Target class: Other protein kinase WEE family; Enzyme; Other protein kinase group; Protein Kinase; Kinase
Chemical probes: Adavosertib (high quality), ML118, ML177, PD081494, PD083322, WEE1-IN-4, ZNL-02-096 (high quality)
Gene: Protein-coding gene on chromosome 11 (9,573,668 to 9,593,457, forward strand). Ensembl gene ENSG00000166483.
Subcellular location: Nucleus
Subcellular location (Human Protein Atlas): Nucleoli
Pathways (Reactome):
Cell Cycle: Chk1/Chk2(Cds1) mediated inactivation of Cyclin B:Cdk1 complex; Cyclin A/B1/B2 associated events during G2/M transition; Cyclin A:Cdk2-associated events at S phase entry; Cyclin E associated events during G1/S transition; G2/M DNA replication checkpoint; Polo-like kinase mediated events
Hemostasis: Factors involved in megakaryocyte development and platelet production
Gene Ontology:
Molecular function: protein binding; protein tyrosine kinase activity; ATP binding; magnesium ion binding; non-membrane spanning protein tyrosine kinase activity; protein kinase activity
Biological process: negative regulation of G2/M transition of mitotic cell cycle; G2/M transition of mitotic cell cycle; negative regulation of G1/S transition of mitotic cell cycle; positive regulation of DNA replication; mitotic cell cycle
Cellular component: nucleolus; nucleus; cytoplasm; nucleoplasm
Genetic constraint (gnomAD): Loss-of-function variants: 13 observed, 50.99 expected, observed/expected ratio (o/e) 0.25, 90% interval 0.17 to 0.41. The upper end of that interval is the gene's LOEUF score, 0.41, which puts it in group 1 of 6, group 1 being the genes least tolerant of losing a copy. Missense variants: 442 observed, 563.79 expected, observed/expected ratio (o/e) 0.78, 90% interval 0.72 to 0.85. Synonymous variants: 253 observed, 210.86 expected, observed/expected ratio (o/e) 1.2, 90% interval 1.08 to 1.33.
Homologues: Orthologues: chimpanzee WEE1 (99% identical), macaque WEE1 (99% identical), pig WEE1 (97% identical), dog WEE1 (97% identical), rabbit WEE1 (93% identical), rat Wee1 (92% identical), mouse Wee1 (91% identical), guinea pig WEE1 (88% identical), tropical clawed frog wee1 (72% identical), zebrafish wee1 (63% identical), Drosophila melanogaster Wee1 (35% identical). Paralogues in human: WEE2 (41% identical), PKMYT1 (20% identical), EIF2AK4 (18% identical), EIF2AK3 (18% identical), STK35 (17% identical), EIF2AK2 (16% identical), EIF2AK1 (15% identical), PDIK1L (11% identical).
Diseases named in the same sentence as WEE1 in open-access papers:
WEE1 is named in the same sentence as 429 diseases in open-access papers, as found by Europe PMC text mining. Sharing a sentence is not in itself a finding about the gene and the disease. The quoted sentences say what the papers report.
breast cancer (170 papers, 2007 to 2026). A primary or metastatic malignant neoplasm involving the breast. "Elevated WEE1 levels are associated with aggressiveness in diverse human cancers including glioma, melanoma, and breast cancer." (PMID 40551232, 2025). "High Wee1 expression was reported to be strongly associated with increased cancer metastasis and poor survival in several cancer types, including breast cancer, ovarian cancer, colorectal cancer and laryngeal cancer." (PMID 37296592, 2023). "Another study in breast cancer cells showed that the loss of PTEN which would enhance replication stress leads to Wee1 inhibition sensitivity." (PMID 38020882, 2023). "The knockdown of AATK expression caused a significant increase in CCND1 and WEE1 expression in the breast cancer cell line MCF-7, HEK293T and the melanoma cell line Sk-Mel13." (PMID 35902728, 2022). "WEE1, a tyrosine kinase regulator of the cell cycle, is over-expressed in several cancer types, including hepatocellular carcinoma and breast cancer and is also associated with poor disease free survival in malignant melanoma." (PMID 23531080, 2013). "WEE1 has been associated with survival in several other cancer types including glioblastoma, malignant melanoma and breast cancer." (PMID 23531080, 2013). "WEE1 is overexpressed in various cancer types, including breast cancer, leukemia, and melanoma, and may be associated with poor prognosis." (PMID 40949156, 2025). "A recent study in basal-like breast cancer cells suggests that loss of PTEN may be one of the strongest markers of Wee1 inhibitor sensitivity." (PMID 35251998, 2022). "Interestingly, breast cancer cells treated with paclitaxel are reported to down-regulate Wee1 expression, suggesting that loss of Wee1 activity is an important step in paclitaxel mediated-cell killing." (PMID 29088738, 2017). "XRCC1 loss amplifies the sensitivity of pancreatic cancer cells to β-lapachone, triple negative breast cancers to the ATM, ATR, and Wee1 inhibitors, liver adenocarcinoma HepG2 to γ rays, and breast cancer cells to cisplatin, camptothecin, and MMS." (PMID 40271221, 2025). "Integrating WEE1 inhibition into precision medicine through biomarker-driven patient selection has the potential to transform breast cancer treatment and provide a potential treatment for patients with aggressive and therapy-resistant diseases." (PMID 40565165, 2025). "In the survival analysis of patients with breast cancer stratified by WEE1 expression in TNBC and non‐TNBC, a significantly shorter metastasis‐free survival was observed in patients with TNBC who had high WEE1 expression but not in those with non-TNBC." (PMID 40551232, 2025). "Thus, inhibiting WEE1 may overcome resistance to standard therapy in ER + breast cancer, and it holds significant implications for Rb-deficient, ER + resistant breast cancer cells." (PMID 40949156, 2025). "As preclinical studies have demonstrated the efficacy of WEE1 kinase inhibitors in breast cancer, clinical evaluation of WEE1 inhibitors has begun." (PMID 40565165, 2025). "This section of the review highlights the key preclinical studies evaluating WEE1-inhibitor-based combination therapies in breast cancer models." (PMID 40565165, 2025). "In a comprehensive investigation involving ovarian cancer, chronic myeloid leukemia, and breast cancer, the surviving cells following WEE1 inhibitor treatment were subjected to sequencing analysis." (PMID 38231277, 2024). "WEE1 is targeted to inhibit the growth of breast cancer cells resistant to endocrine therapy and CDK4/6 inhibitors." (PMID 36358806, 2022). "In studies in breast cancer cells, inhibition of the cell cycle G2M checkpoint regulator Wee1 increased TRAIL mediated apoptosis in TNBC in part by upregulating DRs on the breast cancer cells." (PMID 36496977, 2022).
breast cancer (continued). "In breast cancer cells, the deletion of KDM4B not only reduces the transcription of WEE1, CCND1, and CCNA1, but also disrupts the estrogen-induced cell cycle G1-S phase transition, causing breast cancer cells to stall at the G2-M phase or G1-S phase." (PMID 35186950, 2021). "We then investigated the consequence of WEE1 chemical inhibition, which is less drastic than the WEE1 knock‐out, in breast cancer cell lines according to the TN/non‐TN subtypes." (PMID 34227743, 2021). "More specifically, WEE1 and ATR inhibitors caused the synergistic killing of acute myeloid leukemia (AML), biliary tract, and breast cancer cells, likely due to problems arising in S-phase and G2/M." (PMID 34359691, 2021). "The addition of WEE1 inhibitor to paclitaxel increased total time in mitosis compared to either treatment alone in HELA cells and can sensitize breast cancer cells to paclitaxel treatment, providing a rationale of combining paclitaxel with WEE1 inhibitor." (PMID 34269904, 2021). "In breast cancer, targeting WEE1 with AZD1775 has been recently investigated by others as a promising strategy in combination therapeutic approaches in different subtypes of the disease, particularly in preclinical models of TNBC." (PMID 34277427, 2021). "In recent years, a number of preclinical studies have focused on understanding the functionality of WEE1 in breast cancer cells, particularly those with defective cell cycle regulation." (PMID 34277427, 2021). "Studies have shown that WEE1 was highly expressed in many types of cancers, such as breast cancers, hepatocellular carcinoma, glioblastoma, melanoma." (PMID 33986660, 2021). "Reduced WEE1 expression has been detected in breast cancer compared with normal tissues, independently of the tumor grade." (PMID 32958072, 2020). "Regulation of CDKs by WEE1 is found in various cancers, including glioblastoma, lung carcinoma, and breast cancer." (PMID 33324542, 2020). "The predominance of WEE1 deletion events (6.3% versus 3.25% of cases with amplification) was also observed in breast cancer, in line with its reduced expression." (PMID 32958072, 2020). "In the breast cancer cell line CAL51, Wee1 is overexpressed and inhibition by MK-1775 is associated with a functional loss of Wee1 leading to cell death underlining the essential role of Wee1 in tumor cell viability." (PMID 31015476, 2019). "A very recent study reported that treatment with ATR plus Wee1 inhibitors led to tumor remission and inhibited metastasis with minimal side effects in an orthotopic breast cancer model." (PMID 31362335, 2019). "One such approach is using cell cycle checkpoint inhibitors such as WEE1 or Chk1 inhibitors in combination with DNA damaging agents (i.e., platinum) or PARP inhibitors in BRCA1 deficient breast cancer." (PMID 30993195, 2019). "And indeed WEE1 is found to be expressed at high levels in various cancer types including breast cancer and has been identified as one of the molecules in the tamoxifen resistance pathway." (PMID 30404658, 2018). "As a result of this mechanism of action, WEE1 inhibitors have entered clinical trials as chemo-sensitizers of various tumors, such as breast cancer, leukemia and melanoma." (PMID 29899842, 2018). "FKA induces G2M arrest in cell cycle progression of HER2-overexpressing breast cancer cell lines through inhibition of Cdc2 and Cdc25C phosphorylation and downregulation of expression of Myt1 and Wee1 leading to increased Cdc2 kinase activities." (PMID 28335434, 2017). "We now show that kinases ATR, CHK1 and WEE1 when silenced confer sensitivity to cisplatin of multiple basal type breast cancer cells and cisplatin resistant MB-MDA-231 breast cancer cells." (PMID 28262781, 2017).
breast cancer (continued). "Herceptin plus FKA treatment leads to an enhanced growth inhibitory effect on HER-2 overexpressing breast cancer cell lines through downregulation of Myt1, Wee1, Skp2, survivin, and XIAP." (PMID 28335434, 2017). "Our study reveals that the c-Jun/Wee1 axis is an important target for TTP in breast cancer development, and the findings have therapeutic potential for developing treatment of tumor patients." (PMID 26497679, 2015). "In this study, we observe that TTP induces Wee1 expression in breast cancer cells which can prevent cell progression into the G2 stage and cause cell cycle arrest at the S phase." (PMID 26497679, 2015). "It will be interested in investigating the role of HuR in TTP-mediated induction of Wee1 expression in breast cancer cells in further exploration." (PMID 26497679, 2015). "In accordance with this, high expression of Wee1 has previously been described in human glioblastoma, osteosarcoma, breast cancer and melanoma." (PMID 23767999, 2013). "WEE1 inhibition, in breast cancer, results in a significant decrease in cell proliferation and increased apoptotic levels." (PMID 23531080, 2013). "Elevated levels of Wee1 have been reported in human glioblastoma, osteosarcoma, breast cancer and melanoma, whilst down-regulation, on the other hand, has been observed in non-small-cell lung cancer." (PMID 23767999, 2013). "The specific role of WEE1 in breast cancer is incompletely understood." (PMID 40565165, 2025). "However, in tumors that rely on G2/M checkpoint arrest for DNA damage repair, preclinical and clinical studies that explored WEE1 inhibition showed a reduction in the growth of a wide variety of cancers, including breast cancer." (PMID 40565165, 2025). "Herein, we review the role of WEE1 inhibition therapy in breast cancer." (PMID 40565165, 2025). "Inhibition of WEE1 was shown to sensitise trastuzumab-resistant BCSCs to chemotherapy-induced apoptosis, and co-administration of an ATR and WEE1 inhibitor showed an elevated synergistic cytotoxic effect in BCSCs isolated from an orthotopic breast cancer xenograft mouse model." (PMID 36980782, 2023). "Due to defects in the G1/S checkpoint and other DDR components, cancer cells are more reliant on the G2/M checkpoint as demonstrated by Wee1 overexpression in various tumors (e.g., glioblastoma and breast cancer) making it an attractive drug target for therapy." (PMID 38020882, 2023). "The combination of ATR and WEE1 inhibitors were also found to have tumor-selective synthetic lethality, leading to tumor remission and inhibited metastasis with minimal side effects in an orthotopic breast cancer model." (PMID 36378528, 2023). "A study in breast cancer found that inhibition of Wee1 expression could target and correct cell cycle checkpoint abnormalities, thereby overcoming tumor cell resistance to cisplatin." (PMID 37102239, 2023). "Furthermore, the combination of AURK and WEE1 inhibitors, yields synergistic cell death selectively in RB-deleted ERα+ breast cancer cells." (PMID 36358806, 2022). "In particular, thanks to this approach, authors could identify a breast cancer patient subset (luminal breast cancer) that overexpressed Wee1, where its inhibition could be suggested as a potential therapeutic strategy." (PMID 34639030, 2021). "Thus, targeting WEE1 is a promising anti-cancer therapeutic strategy in standard therapy resistant ER+ breast cancer." (PMID 34277427, 2021). "Although this data suggests a role of increased WEE1 in ER+ breast cancer progression, further studies are needed to determine whether increased WEE1 expression correlate with resistance to antiestrogens or CDK4/6 inhibitors." (PMID 34277427, 2021).
breast cancer (continued). "In stromal breast cancer, Wee1 expression was investigated using immunohistochemistry." (PMID 34639030, 2021). "The goal of this study was to investigate whether inhibition of WEE1 is an effective therapy for breast cancer cells that have progressed on endocrine therapies and are intrinsically resistant to CDK4/6 inhibitors." (PMID 34277427, 2021). "In breast cancer, miR-381 inhibits WEE1 and blocks the G2/M transition." (PMID 33324542, 2020). "Moreover, WEE1 inhibition has already been reported to synergistically inhibit breast cancer growth in combination with cisplatin in xenograft models." (PMID 30404658, 2018). "In addition, FKA enhanced the growth inhibitory effect of HER2 specific antibody Herceptin on HER2-overexpressing breast cancer cell line by down-regulation of Myt1, Wee1, survivin, and XIAP." (PMID 28335434, 2017). "In the context of our previous data implicating WEE1 as a cancer target, these immunohistochemical data suggest that the use of WEE1 inhibitors may be appropriate in a significant subset of breast cancer patients." (PMID 19357772, 2009). "Similarly, heightened expression or increased activity of WEE1 was observed in glioma, liver cancer models, medulloblastoma, seminoma, breast cancer, and osteosarcoma." (PMID 38231277, 2024). "In this study, we used endocrine sensitive and resistant breast cancer cell line pairs to evaluate whether the WEE1 inhibitor, AZD1775, as a single agent or in combination with antiestrogens or CDK4/6 inhibitors, is a reasonable therapy option for inhibiting growth of resistant cells." (PMID 34277427, 2021). "For breast cancer patients, our data underscore that overexpression of nuclear and/or cytoplasmic Cyclin E could be used as a selection criterion for treatment with drugs that target replication stress, including inhibitors of WEE1 and ATR." (PMID 32964114, 2020). "Furthermore, we identified a subset of breast tumours that highly express WEE1 suggesting that WEE1 could be a novel therapeutic target in breast cancer." (PMID 19357772, 2009). "The rationale for this is supported from our previous study in ER+ breast cancer models where the treatment with AURK and WEE1 kinase inhibitors resulted in the upregulation of TNFα signaling." (PMID 41285729, 2025). "Adavosertib is a tyrosine kinase WEE1 inhibitor used to improve the outcome in triple-negative breast cancer, vinorelbine is an agent to treat NSCLC and breast cancer, and capivasertib is AKT inhibitor used in the treatment of breast cancer." (PMID 37961281, 2023). "In ER+ breast cancer cell models made resistant to ribociclib, the combination of AZD1775 (WEE1 inhibitor) and ribociclib inhibited proliferation in resistant cells." (PMID 36358806, 2022). "The approach of simultaneous inhibition of WEE1 and ATR has emerged very recently and appears promising based on preclinical studies of breast cancer and AML." (PMID 34359691, 2021). "The preclinical data presented in this study provides a rationale for using WEE1 inhibitors as a promising novel therapy for endocrine resistant and CDK4/6 inhibitor resistant breast cancer." (PMID 34277427, 2021). "In multiple ER+ breast cancer cell lines, the WEE1 inhibitor AZD1775 (MK1775), which works to decrease WEE1 activity at the G2/M checkpoint, has been shown to increase sensitivity in cells resistant to CDK4/6 inhibitors and cause cell death." (PMID 34830174, 2021). "WEE1 is highly expressed in brain cancer, breast cancer, and melanoma, while CHEK1 expression is higher in the tumor tissues of breast cancer, colon cancer, and liver cancer." (PMID 31387297, 2019). "In breast cancer models, combination of ATR and WEE1 inhibitors inhibits tumor cells progression and metastasis process." (PMID 31412533, 2019).